SUSD4 (sushi domain containing 4)
Diseases named in the same sentence as SUSD4 in open-access papers (continued):
Sharing a sentence is not in itself a finding about the gene and the disease.
cancer (continued). "Nonetheless, the primary aim of this study was to deliver a comprehensive pan-cancer analysis of SUSD4, and more intricate validation of gene function will be pursued in future investigations." (PMID 38579174, 2024). "Through systematic pan-cancer analysis, our study reveals a dualistic nature of SUSD4 expression in tumors, impacting prognosis differently depending on the cancer type." (PMID 38579174, 2024). "Upon comparing SUSD4 expression levels between cancerous and normal tissues, we observed pronounced elevation exclusively in select cancer types." (PMID 38579174, 2024). "Our systematic pan-cancer analysis has elucidated a dualistic nature in the role of Sushi domain-containing protein 4 (SUSD4) expression within tumors." (PMID 38579174, 2024). "Taken together, these data suggest that SUSD4 independently inhibits both growth and migration of cancer cells." (PMID 26480818, 2015). "The results indicated that SUSD4 was an independent biomarker for cancer-specific survival (p = 0.040; HR: 0.34; 95 % CI: 0.1 – 0.9)." (PMID 26480818, 2015). "Possibly, the CAFs secrete factors affecting the cancer cells and thereby enhance the anti-tumor effects of SUSD4." (PMID 26480818, 2015). "Building upon this premise, we postulate that SUSD4 may exert a discernible influence on tumorigenesis and cancer progression." (PMID 38579174, 2024). "Conversely, a significant negative correlation trend was observed in cancers with a better prognosis associated with high SUSD4 expression." (PMID 38579174, 2024). "SUSD4 was studied across a variety of cancer types in this study." (PMID 38579174, 2024). "CXCL17 and CX3CL1 were positively correlated with SUSD4 expression level in most types of cancer." (PMID 38579174, 2024). "Furthermore, we assessed the relationship between SUSD4 expression level and DNA methylation, as DNA methylation is known to play a role in the epigenetic mechanisms of cancer." (PMID 38579174, 2024). "Thus, recognizing this void in the literature, our study endeavors to bridge this gap by methodically scrutinizing the correlation between SUSD4 expression levels and a comprehensive spectrum of cancer types." (PMID 38579174, 2024). "Moreover, our survival analysis unveiled two discernible impacts of SUSD4 expression levels on prognosis, thereby underscoring its potential utility as a prognostic biomarker across diverse cancer contexts." (PMID 38579174, 2024). "The role of SUSD4 in cancer progression has largely remained elusive." (PMID 38579174, 2024). "Overall, SUSD4 exhibits a dichotomous relationship with prognosis in different types of cancer." (PMID 38579174, 2024). "Additionally, in cancers with poor prognosis and high SUSD4 expression (including DLBC, THYM, COADREAD, KIRP, LIHC), a positive correlation trend was observed with inhibitory-related genes." (PMID 38579174, 2024). "Kaplan-Meier analyses showed that the presence of SUSD4 transcripts in the tumor tissues was significantly associated with improved cancer specific survival (p = 0.009), but not recurrence free survival (p = 0.220)." (PMID 26480818, 2015). "Interestingly, we found a negative correlation between SUSD4 expression level and DNA methylation mutations in 18 types of cancer." (PMID 38579174, 2024). "Cancer associated fibroblasts in turn expressed EGFR but not SUSD4." (PMID 36578014, 2022). "In addition, we detected SUSD4 expression on tumor infiltrating cells in several types of cancer." (PMID 26480818, 2015). "Given that the primary focus of this study does not involve elucidating the specific mechanisms of SUSD4 in cancer, further exploration in this regard was not pursued." (PMID 38579174, 2024). "Additionally, our analysis revealed strong correlations between SUSD4 expression level and both CNV and DNA methylation in various cancers." (PMID 38579174, 2024).
cancer (continued). "This assay primarily measured cell proliferation of the cancer cells, but since we only observed an effect of SUSD4 in co-culture with CAFs and not control fibroblasts, this cannot be the only important factor." (PMID 26480818, 2015).
tumor (5 papers, 2015 to 2024). "COREAD was prominent in previous results, both in terms of immune correlation, survival prognosis, and tumor heterogeneity in association with SUSD4 expression level." (PMID 38579174, 2024). "Correlation analyses with immune-related genes highlight SUSD4’s potential as a prognostic biomarker and its association with tumor immunity." (PMID 38579174, 2024). "In conclusion, we provide further evidence for a tumor suppressive role of SUSD4 and we deciphered the underlying mechanism." (PMID 36578014, 2022). "Associations between SUSD4 expression in tumor cells and clinical parameters showed that SUSD4+ tumors had a tendency (p = 0.066) to be smaller." (PMID 26480818, 2015). "A higher number of SUSD4+ infiltrating cells in the tumor stroma were associated with a diagnosis at an earlier age (p = 0.006)." (PMID 26480818, 2015). "The increased level of SUSD4a protein in activated T cells provides further explanations for the finding that levels of SUSD4+ infiltrating cells are associated with increased survival, as an active anti-tumor T-cell response would be beneficial to patients." (PMID 26480818, 2015). "Additionally, our analysis of SUSD4 correlation with immune-related genes and tumor infiltration unveiled a consistent trend: in instances where elevated SUSD4 expression was linked to poorer prognosis, a positive correlation with immune-related genes and infiltrating cells was evident." (PMID 38579174, 2024). "Accordingly, these findings underscore the need for further comprehensive investigation and discussion to elucidate the mechanistic underpinnings of SUSD4 in tumor immunity and its impact on patient outcomes." (PMID 38579174, 2024). "Comparison of SUSD4 expression levels in normal and tumor samples was also performed using data obtained from the GTEx database." (PMID 38579174, 2024). "We evaluated the prognostic significance of SUSD4 expression levels in various tumor types using the log-rank test." (PMID 38579174, 2024). "The aim of the study was to investigate the molecular mechanism by which SUSD4 inhibits tumor progression." (PMID 36578014, 2022). "We previously revealed that SUSD4 can act as complement inhibitor and as a potential tumor suppressor." (PMID 36578014, 2022). "We used the ESTIMATE algorithm, including stromal score, immune score, and ESTIMATE score, to estimate the relationship between SUSD4 expression level and tumor microenvironment (TME)." (PMID 36686789, 2022). "Interactions of SUSD4 with growth factor receptors that play well-characterized roles in tumor progression and development were identified in addition to an autophagy-promoting effect." (PMID 36578014, 2022). "Here, we show that SUSD4 is expressed by epithelial tumor cells, in which it affects migration and invasion, and in tumor-infiltrating CD8+ and CD4+ T cells." (PMID 26480818, 2015). "The intensity of the SUSD4 staining in tumor cells was scored 0, 1 or 2 and the number of SUSD4+ infiltrating cells in each section was counted." (PMID 26480818, 2015). "Cox uni- and multivariable analyses were performed in order to determine the prognostic value of SUSD4 expression in tumor cells." (PMID 26480818, 2015). "We evaluated the correlation between the expression level of SUSD4 and tumor heterogeneity using four metrics: microsatellite instability (MSI), tumor mutational burden (TMB), mutational burden-assessed tumor heterogeneity (MATH), and homologous recombination deficiency (HRD)." (PMID 38579174, 2024). "Therefore, a correlation was found between SUSD4 expression levels and the expression levels of multiple immune-related genes in different tumor tissues." (PMID 38579174, 2024).
tumor (continued). "SUSD4 expression levels in normal and tumor samples were compared using the TCGA database." (PMID 38579174, 2024). "Through tumor heterogeneity analysis, it was hypothesized that SUSD4 has the potential to be an immunotherapeutic target." (PMID 38579174, 2024). "Based on these findings, we propose that SUSD4 may have a mechanism that affects immune regulation and thus influences tumor prognosis." (PMID 38579174, 2024). "We first confirmed that SUSD4 acts as tumor suppressor in vivo in a syngeneic mouse model." (PMID 36578014, 2022). "The syngeneic model thus provides further support for a tumor suppressive effect of SUSD4." (PMID 36578014, 2022). "The previously identified complement inhibitory function of SUSD4 could theoretically be beneficial for the tumor." (PMID 36578014, 2022). "The SUSD4-expressing tumor-infiltrating cells were identified as CD4+ and CD8+ T cells." (PMID 26480818, 2015). "Based on our present study it is hard to determine whether the tumor-suppressing effect of SUSD4 stems from the complement function of this protein or whether it is another, independent function." (PMID 26480818, 2015). "Tissue stainings revealed that both tumor cells and tumor-infiltrating cells expressed SUSD4." (PMID 26480818, 2015). "The human Sushi Domain-Containing Protein 4 (SUSD4) was recently shown to function as a novel inhibitor of the complement system, but its role in tumor progression is unknown." (PMID 26480818, 2015). "Interestingly, SUSD4 was also found to be expressed by tumor infiltrating T cells." (PMID 36578014, 2022). "Furthermore, in addition to its complement-regulatory properties, we have previously proposed a tumor suppressive effect of SUSD4, yet the underlying molecular mechanism has not previously been addressed." (PMID 36578014, 2022). "Hence indicating that SUSD4 is expressed by the cancerous cells rather than the tumor-associated stromal cells." (PMID 36578014, 2022). "While no tumors could be detected in the group transplanted with 2 × 106 SUSD4-expressing cells, seven out of 10 mice transplanted with mock control cells developed tumors and a significant difference in tumor volume between the two groups was observed 56 days post transplantation." (PMID 36578014, 2022). "Although SUSD4 has previously been described as a novel complement inhibitor, it is likely that the protein’s anti-tumor effects are independent of its complement-related functions." (PMID 26480818, 2015). "Furthermore, SUSD4 is expressed by CD4+ and CD8+ T cells in tumor stroma, which correlates with good prognosis." (PMID 26480818, 2015). "SUSD4 is not the first complement inhibitor implied to regulate tumor growth." (PMID 26480818, 2015). "While the expression of SUSD4 did not affect EGFR downstream signaling or Beclin-1 dissociation from Rubicon, it affected the activation of the tumor suppressor LKB1 and AMPKα1." (PMID 36578014, 2022).
endocrine system disorder (1 paper, 2024). A disease involving the endocrine system. "For the CIDR+12 h top network, involved in Endocrine system disorders, Hereditary disorders and Organismal injury and abnormalities, NF-κB is linked to various hub genes, such as SUSD4, which negatively regulates complement activation, and ALDH1B1, which links to various aldehyde dehydrogenases." (PMID 38547106, 2024).
neurodevelopmental disorder (1 paper, 2021). A behavioral and cognitive disorder with onset during the developmental period that involves impaired or aberrant development of intellectual, motor, or social functions. "In order to uncover the potential link between SUSD4 and neurodevelopmental disorders, we sought to identify the role of SUSD4 in brain development and function, by analyzing the phenotype of a Susd4 constitutive loss-of-function mouse model." (PMID 33661101, 2021). "Thus, mutations in the Susd4 gene might contribute to the etiology of neurodevelopmental disorders by impairing synaptic plasticity at many synapse types." (PMID 33661101, 2021). "Understanding the molecular mechanism linking activity-dependent degradation of GluA2 and the SUSD4/NEDD4 complex will thus be of particular importance for our understanding of the etiology of these neurodevelopmental disorders." (PMID 33661101, 2021). "Altogether these studies point to a potential role of SUSD4 in synapse formation and/or function and in the etiology of neurodevelopmental disorders." (PMID 33661101, 2021).
SUSD4 also shares sentences with these, for which no sentence is quoted: asthma (1 paper); autism spectrum disorder (1); breast tumor (1); colorectal (1); Fryns syndrome (1); inflammatory bowel disease (1); Intellectual disability (1); lung adenocarcinoma (1); lymphoma (1); myeloma (1); ovarian carcinoma (1).